CCND1 (cyclin D1)
Diseases named in the same sentence as CCND1 in open-access papers (continued):
Sharing a sentence is not in itself a finding about the gene and the disease.
testicular teratoma (1 paper, 2018). "Our results suggested that the expression of a cell cycle gene, Ccnd1, was upregulated by Dnd1 deficiency via the loss of Ezh2 expression and of H3K27me3 in Dnd1ter/ter testicular germ cells, and this molecular pathway may play a role in testicular teratoma development in Dnd1ter/ter testes." (PMID 29378702, 2018). "Among them, we chose Ccnd1 as a promising candidate, because Ccnd1 is known to promote testicular teratoma formation." (PMID 29378702, 2018).
Thoracic neoplasm (1 paper, 2023). "The SPP1 network contains several immune-related proteins as well as cancer-related proteins (e.g., Neoplasia of cells, CCND1, Thoracic neoplasm and Metastatic solid tumor)." (PMID 37513116, 2023).
thymic lymphomas (1 paper, 2021).
thyroid nodule (1 paper, 2019). A small circumscribed mass in the THYROID GLAND that can be of neoplastic growth or non-neoplastic abnormality. "In addition, we investigated the prospect of a new preoperative cytological strategy for the detection of thyroid nodules using a combination of cyclin D1 immunostaining and genetic sequence analysis." (PMID 30885146, 2019).
Tinnitus (1 paper, 2024). Tinnitus is an auditory perception that can be described as the experience of sound, in the ear or in the head, in the absence of external acoustic stimulation. "Subsequently, through Mendelian randomization analysis, we found that HIF1A and CCND1 are significantly associated with tinnitus disease." (PMID 39315211, 2024). "MR analysis indicated a significant association between HIF1A and CCND1 with tinnitus." (PMID 39315211, 2024). "Furthermore, through MR analysis, HIF1A was identified as a potential protective factor, significantly negatively correlated with the risk of tinnitus (OR = 0.78, p = 0.008), while CCND1 showed a positive correlation (OR = 1.22, p = 0.04)." (PMID 39315211, 2024). "The results suggest that HIF1A has a potential protective role in the development of tinnitus, while CCND1 has a promoting effect." (PMID 39315211, 2024). "The results showed significant associations of HIF1A (OR [95 %] = 0.78 [0.65, 0.94], p = 0.008) and CCND1 (OR [95 %] = 1.22 [1.00, 1.49], p = 0.04) with tinnitus in MR analysis IVW results." (PMID 39315211, 2024). "Mendelian randomization analysis revealed that HIF1A (OR [95 % CI] = 0.78 [0.65, 0.94], P = 0.008) and CCND1 (OR [95 % CI] = 1.22 [1.00, 1.49], P = 0.04) exhibited significant results with tinnitus." (PMID 39315211, 2024). "HIF1A may act as a protective target for tinnitus, while CCND1 may promote its occurrence and development." (PMID 39315211, 2024). "Colocalization analysis of HIF1A and CCND1 with tinnitus indicated no shared colocalization for both HIF1A (PH4 = 0.34) and CCND1 (PH4 = 0.02)." (PMID 39315211, 2024).
undifferentiated endometrial carcinoma (1 paper, 2018). "Additionally, one reportedly undifferentiated endometrial carcinoma also contained a c-terminal CCND1 mutation, while an endometrial serous carcinoma contained an n-terminal cyclin D1 mutation of unknown functional significance." (PMID 29969496, 2018).
uterine adenosarcomas (1 paper, 2023). "Material and Method: In this study, DNA mismatch repair proteins, p16, cyclin D1, ER, PR, and CD10 were examined in uterine adenosarcoma cases using immunohistochemistry." (PMID 35876683, 2023). "Further investigations are required to determine the importance of p16, cyclin D1, and MSI in uterine adenosarcomas." (PMID 35876683, 2023). "Additional studies are needed to enable accurate predictions of the effect of p16 and cyclin D1 expression and MSI in uterine adenosarcoma cases." (PMID 35876683, 2023). "First, p16, cyclin D1, ER, PR, and CD10 expression in uterine adenosarcomas was evaluated to determine the possible impacts on the prognosis." (PMID 35876683, 2023).
vocal cord polyp (1 paper, 2013). "The incidence of cyclin D1 expression was 0% (0/5) in vocal cord polyp and 0% (0/5) in atypical hyperplasia." (PMID 24223635, 2013). "Our results have demonstrated that the expression of cyclin D1 in laryngeal SCC tissues is markedly higher than that in atypical hyperplasia and vocal cord polyp tissues (P<0.05)." (PMID 24223635, 2013). "Ang-2 and cyclin D1 protein expression was not present in 5 cases of atypical hyperplasia or 5 cases of vocal cord polyps." (PMID 24223635, 2013).
xerostomia (1 paper, 2021). Dryness of the mouth resulting from reduced salivary secretion. "Genetic alterations in BRCA2, ERBB3, NOTCH1 and CCND1 were all associated with higher mean grade of toxicity with BRCA2 alteration implicated in all toxicity parameters evaluated including mucositis, early dysphagia, xerostomia and to a lesser extent, late dysphagia." (PMID 34001187, 2021).
ZIKV infection (1 paper, 2022).
tumor (3,508 papers, 1995 to 2026). "Krüppel-like factors (KLFs), components of Wnt signaling, estrogen receptor beta (ERβ) isoforms, cyclin D1, and E-cadherin have been implicated in epithelial-mesenchymal transition, tumor proliferation, and disease progression." (PMID 41898441, 2026). "IL-6 activates tumor cells to induce the expression of STAT3 target genes, which in turn encode proteins that promote tumor growth (such as cyclin D1) and/or survival (such as BCL-2-like protein 1 (BCL-xL)." (PMID 41596531, 2026). "In contrast, MYC, STAT3, CDH1, and CCND1 were significantly downregulated in tumor tissues compared to normal controls, suggesting a loss of tumor-suppressive or differentiation-related functions." (PMID 40766612, 2025). "Downregulation of Cyclin D1 expression can cause cell cycle arrest in the G0/G1 phase and inhibit the proliferation of tumor cells." (PMID 39803233, 2025). "This is critical, as cyclin D1 is known to be overexpressed in various cancers and is associated with poor prognosis and resistance to treatments, and its level is correlated to tumor size." (PMID 40427550, 2025). "Detailed immunoblot analyses revealed that compounds 11a and 11b decreased the expression of endogenousGLI1 protein and its target genes associated with tumor progressionand proliferation, such as Cyclin D1, N-Myc, and Bcl-2, in A549 andDU-145 cancer cells." (PMID 40124057, 2025). "Multiple studies have revealed that CFIm25 levels affect the proliferation of many types of tumor cells, with CFIm25 being mostly tumor-suppressive, in part by causing lengthening of transcripts of the cell cycle gene CCND1." (PMID 40022203, 2025). "Cyclin D1 plays a central role in driving cell cycle progression, and its overexpression is frequently associated with uncontrolled proliferation and tumor development." (PMID 41476794, 2025). "In cancers, failure to properly regulate the G1/S transition due to persistent overexpression of cyclin D1 and other cell cycle regulators contributes to the loss of cell cycle control, enabling tumor cells to proliferate uncontrollably." (PMID 40723282, 2025). "Overexpression of CCND1 has been associated with the development and progression of various tumor types, including NSCLC." (PMID 40002176, 2025). "HG-ESS typically lack ER, PR, and CD10 expression but show strong and diffuse cyclin D1 positivity (>70% of tumor nuclei), which is a key diagnostic discriminator." (PMID 41464215, 2025). "In tumour tissues with stable silencing of circKIAA1797, the expression levels of the proliferation-associated protein Ki67, the cycle-associated protein Cyclin D1, the migration-associated protein RhoA and the apoptosis-associated protein Bcl2 were reduced." (PMID 40176113, 2025). "HACE1 blocks the generation of ROS by Rac1-dependent NADPH oxidases, thereby alleviating the initiation and progression of tumor cells caused by DNA oxidative damage and cyclin D1-driven hyperproliferation." (PMID 40948788, 2025). "Although BCL2 and Cyclin D1 showed associations with tumor aggressiveness, their prognostic roles remain uncertain." (PMID 41189865, 2025). "In another mouse model, orthotopic implantation of tumor cells of the MB49 type has been associated with a drop in Cyclin D1 and a decrease in COX‐2 protein production." (PMID 41179371, 2025). "A statistically significant association was found between cyclin D1 expression and tumor grade (p = 0.001)." (PMID 41541922, 2025). ",37TP53 mutations, ATM loss, MDM2 amplification, and cyclin D1 amplification are also shown to occur more frequently in luminal B versus A tumours." (PMID 39921934, 2025).
tumor (continued). "Tob negatively regulates the cyclin D1 gene by recruiting HDAC to the cyclin D1 promoter, which explains, at least in part, why Tob deficiency promotes spontaneous tumor development." (PMID 40169858, 2025). "In vivo, AT7519 effectively inhibited the AM tumor growth bearing CDK4 gain + CCND1 gain, CDK4 gain + p16INK4A loss or only CDK4 gain, whereas palbociclib was effective in mouse models with CDK4 gain + CCND1 gain and CDK4 gain + p16INK4A loss." (PMID 39598629, 2024). "Low nuclear and low cytoplasmic cyclin D1 co-expression showed a significant association with a high tumour grade (adjusted p value = 0.035)." (PMID 38612869, 2024). "For example, the PKM2/β-catenin complex is recruited to the CCND1 promoter, which encodes cyclin D1, and promotes cyclin D1 expression, which promotes tumorigenesis and tumor cell proliferation." (PMID 38933335, 2024). "Epithelial–mesenchymal transition (EMT) plays a significant role in tumor invasion and metastasis, with associated features including the high expression of cyclin D1 and loss of expression of E-cadherin." (PMID 38344198, 2024). "We also identified a CCND1 mutation (encoding cyclin D1) at c.723G > A in the E4 region, with a variant frequency of 100%, indicating that almost all tumor cells carry this mutation." (PMID 39058871, 2024). "A recent study reports that METTL16 was upregulated in GC, exerting a crucial role in the growth of tumor in vivo, which are associated with cyclin D1 expression by blocking G1/S phase." (PMID 39009956, 2024). "Several genes associated with tumour cell proliferation and survival (CCND1, AKT1 and CD44) were more highly expressed in p16-/HPV- tumours relative to p16+/HPV+." (PMID 39328208, 2024). "RECQL4, UTP6, CCNT1, and NSUN5 were enriched in the regulation process of cyclin dependent protein kinase activity, Cyclin D1 is one of the effectors of tumor gene Neu and Ras causing malignant transformation of cells in breast cancer." (PMID 39095659, 2024). "Hyperactivation of Wnt signal pathway leads to translocation and accumulation of β-Catenin inside the nucleus which can then serve as a transcription factor for expression of target genes like cyclin D1 causing tumor growth and proliferation." (PMID 38168547, 2024). "CCND1 is closely associated with the cell cycle regulation in tumor cells, and one of its oncogenic isoforms, CCND1b, exerts distinct effects on CRC compared to its normal splicing isoform, CCND1a, due to the production of unique C-terminal protein sequences." (PMID 39004679, 2024). "We also examined the expression of target genes of NF-kB pathway, including BCL2, MYC, and CCND1, which are also associated with tumor proliferation." (PMID 37716704, 2023). "Huang demonstrated in 264 subjects with OSCC that overexpression of cyclin D1 was associated with higher tumor stage and poorly differentiated carcinomas, higher rate of regional metastases, and worse DFS and OS." (PMID 36982894, 2023). "In PTC, high cyclin D1 levels are associated with larger tumor size, intraglandular metastasis, extrathyroidal extension, lymph node metastasis, and aggressive behavior." (PMID 37427143, 2023). "The C BRCA2 rs15869 allele and the C CCND1 rs7177 allele were statistically likely to be associated with a high histological degree of tumor proliferation, eating high atypia, and invasion rates." (PMID 38156855, 2023). "Elevated levels of p-MNK1 and p-eIF4E correlate with tumor grade and with an increase in Cyclin D1 expression, which is associated with tumor recurrence, increased tumor size, and poor prognosis." (PMID 36994107, 2023). "The p-value for the association of cyclin D1 with the grade of the tumor was 0.157, which was statistically insignificant." (PMID 37007344, 2023).
tumor (continued). "Most of the reported mutated genes were reported in both the primary and metastasis tissues, except KRAS G12A and NEK E379K mutations that were found in primary tumors and CCND1 G103R in the metastasis tumor." (PMID 38003476, 2023). "The causative role of Cyclin D1 in ccRCC tumor progression is highlighted by the fact that CCND1 knockdown in VHL deficient ccRCC cell lines attenuates xenograft growth in vivo." (PMID 36831657, 2023). "Yet, studies with CCND1-null mice (D1KO) or CCND1 deficient cells have indicated that CCND1 is necessary for tumor development." (PMID 37024471, 2023). "The upregulation of Cyclin D1 protein expression can significantly accelerate the transition from the G1 phase to the S phase, causing excessive cell proliferation and tumor formation." (PMID 38028434, 2023). "MCL1 methylation has been associated with poor overall survival in KIRC patients, while IGF1R and CCND1 methylation have been linked to tumor aggressiveness." (PMID 37744271, 2023). "Amplification of CCND1 occurs in breast tumors and is associated with an increase in tumor proliferation." (PMID 37835528, 2023). "The p-value was 0.001, and a statistically significant association was found between the stage of the tumor and cyclin D1 immunoexpression." (PMID 37007344, 2023). "Dysregulated c-MYC and CYCLIN D1 have shown to be associated with aberrant tumour growth in many human cancers." (PMID 37127581, 2023). "The expression of MDSC marker genes such as Itgam, S100a9, and Clec4e, and tumor proliferation-associated genes, Ccnd1 (Cyclin D1) and Myc (c-Myc), was enhanced after PGE2-administration, indicating that MDSC expansion and tumor growth are promoted by PGE2." (PMID 36932082, 2023). "This region harbors genes associated with tumor progression and cell cycle control, including cyclin D1/PRAD1 and BCL-1." (PMID 37370779, 2023). "NF-κB and AP-1 regulate the expression of multiple genes involved in tumor proliferation and metastasis, including those encoding cyclin D1, cyclin E, Myc, MMP-9, MT1-MMP, uPA, Snail, and ZEB1." (PMID 37894738, 2023). "Several studies have revealed that E2F8 acts as a transcriptional activator, positively increasing the expression of cyclin D1 (CCND1) in tumor cells, and a high expression level of E2F8 has been linked with poor prognosis." (PMID 36814821, 2023). "The possible underlying molecular mechanism involved the cyclin D1 downregulation by inhibiting the expression of hepatoma upregulated protein, which is crucial for tumor proliferation, invasion, and metastasis." (PMID 37375411, 2023). "Despite associations between high CCND1 CN and aggressive tumour characteristics, the prognostic impact of CCND1 CN remains unresolved." (PMID 35459982, 2022). "CCND1 amplification has been associated with immunosuppression of the tumor microenvironment and poor outcomes with immune checkpoint inhibitors." (PMID 35484593, 2022). "The main aim was to investigate associations between CCND1 CN alterations in primary BC tumours and proliferation status, molecular subtype, and prognosis." (PMID 35459982, 2022). "HER2 blockade caused a drop in cyclin D1 abruptly, but it rebounds to high level when tumor recurred." (PMID 36387174, 2022). "Next, through celigo cell counting assay, the findings indicated cell proliferation was facilitated by overexpressed CDC42EP3 and inhibited by silenced CCND1, while silencing of CCND1 relieved promotion of tumor cell growth caused by CDC42EP3 overexpression." (PMID 35365622, 2022). "Among the miRNAs differentially expressed on regorafenib treatment, four miRNAs (miR-494-3p, miR-3714, miR-4327, and miR-8073) were tumor suppressors associated with the decreased expression of cyclin D1." (PMID 35163589, 2022).